ESM1 (endothelial cell specific molecule 1)
Description:
Involved in angiogenesis; promotes angiogenic sprouting. May have potent implications in lung endothelial cell-leukocyte interactions.
Synonyms: endocan
Tractability: Antibody: UniProt places it where antibodies can reach, with medium confidence; UniProt predicts a signal peptide or a membrane-spanning region; its Gene Ontology location is reachable by antibodies, with medium confidence.
Gene: Protein-coding gene on chromosome 5 (54,977,867 to 55,022,671, reverse strand). Ensembl gene ENSG00000164283.
Subcellular location: Secreted
Subcellular location (Human Protein Atlas): Vesicles; Predicted to be secreted
Gene Ontology:
Molecular function: extracellular matrix structural constituent; hepatocyte growth factor receptor binding; integrin binding; protein binding
Biological process: angiogenesis; positive regulation of cell population proliferation; positive regulation of hepatocyte growth factor receptor signaling pathway; sprouting angiogenesis
Cellular component: extracellular matrix; extracellular region
Genetic constraint (gnomAD): Loss-of-function variants: 7 observed, 15.25 expected, observed/expected ratio (o/e) 0.46, 90% interval 0.26 to 0.86. The upper end of that interval is the gene's LOEUF score, 0.86, which puts it in group 3 of 6, group 1 being the genes least tolerant of losing a copy. Missense variants: 178 observed, 230.84 expected, observed/expected ratio (o/e) 0.77, 90% interval 0.68 to 0.87. Synonymous variants: 86 observed, 88.22 expected, observed/expected ratio (o/e) 0.97, 90% interval 0.82 to 1.17.
Homologues: Orthologues: chimpanzee ESM1 (100% identical), macaque ESM1 (96% identical), dog ESM1 (84% identical), rabbit ESM1 (81% identical), guinea pig ESM1 (78% identical), pig ESM1 (78% identical), mouse Esm1 (75% identical), rat Esm1 (74% identical), tropical clawed frog esm1 (68% identical), zebrafish esm1 (47% identical).
Diseases named in the same sentence as ESM1 in open-access papers:
ESM1 is named in the same sentence as 135 diseases in open-access papers, as found by Europe PMC text mining. Sharing a sentence is not in itself a finding about the gene and the disease. The quoted sentences say what the papers report.
breast cancer (20 papers, 2013 to 2024). A primary or metastatic malignant neoplasm involving the breast. "ESM-1 endothelial secreted mediator is elevated in a variety of cancers, including breast cancers, and it has been implicated in playing a role in tumor metastasis in other cancers." (PMID 34072157, 2021). "Interestingly, primary tumor expressing ANGPTL7, MMP3, LCN2, S100A8, and ESM-1 levels that were upregulated in 4T1.2 cells was strongly associated with breast cancer patients’ survival outcomes." (PMID 34072157, 2021). "We hypothesized that ESM-1 is a prognostic factor associated with the aggressive breast cancer progression, higher stage, and pathological grade of breast cancer." (PMID 34072157, 2021). "In conclusion, our results suggest that dissimilarly expression of few mediator encoding genes ANPTl7, MMP3, S100A8, LCN2 ESM1 in primary versus distant metastasis organs and their prognostic and predictive scores in breast cancer cohort may be a helpful to predict future metastasis." (PMID 34072157, 2021). "For example, the activation of TNF-α upregulated ESM1 expression by the RelB subunit of NF-κB in breast cancer cells." (PMID 39309430, 2024). "In the research of breast cancer, ESM1 was found to further enhance the malignant transformation of triple-negative breast cancer cells by activating the AKT/NF-κB/Cyclin D1 pathway." (PMID 36117773, 2022). "We previously discovered that ESM-1 played an important role in the tumorigenesis of breast cancer cells, especially RT-R-TNBC cells, through the regulation of several genes involved in tumor growth, progression, and metastasis in vitro and in vivo." (PMID 36077661, 2022). "ESM1 expression is also upregulated in lung cancer, gastric cancer, breast cancer, bladder cancer, and other malignant tumors and is associated with the inflammatory response and tumor progression." (PMID 36428773, 2022). "A higher expression score of ESM-1 was associated with more metastatic (stage III/IV) and higher pathological grade (grade 2/3) of breast cancers." (PMID 34072157, 2021). "Deep analysis of survival in different cohorts implies, indeed, ESM-1 expression was linked with poor survival (OS, and DSS, and PFI) of breast cancer patients." (PMID 34072157, 2021). "High expression of ESM-1 was also associated with TNBC, HER2+, in some cases, HR+/HER2− breast cancer patients’ survival outcomes." (PMID 34072157, 2021). "We further extend our analysis by comparing the higher expression of ESM-1 associated with TNBC patients and survival in three breast cancer cohorts." (PMID 34072157, 2021). "Taken together, these results suggest for the first time that ESM-1 plays a critical role in tumorigenesis of breast cancer cells, especially RT-R-breast cancer cells, through the induction of cell proliferation and invasion." (PMID 32466580, 2020). "After the first observation of properties of promoting tumor growth of ESM1 from engineered HEK293 cells in a mouse model of human tumor xenograft, ESM1 was later found to be correlated with lung, renal and breast cancers." (PMID 28108731, 2017). "We notified that TET also decreases ESM-1 expression in breast cancer cells, which leads to an inhibition effect of tumor metastasis." (PMID 23762115, 2013). "ESM1 overexpression is closely associated with drug resistance to chemotherapy in breast cancer (BRCA) and has certain impact on the clinical outcome of advanced gastric cancer after chemotherapy, indicating that ESM1 is of potential clinical value in cancer patients." (PMID 37100467, 2023). "Together, data suggested that the ESM-1 gene is overexpressed in metastatic aggressive subtypes of breast cancers and could be an independent prognostic factor." (PMID 34072157, 2021). "Moreover, increased expression of Esm1 enhances the proliferative capacity, colony forming ability, migration and invasiveness of radiotherapy-resistant breast cancer cells all by itself, with its down-regulation reversing these effects." (PMID 34321516, 2021).
breast cancer (continued). "In this study, MBZ inhibited ESM-1 protein in both MDA-MB-231 and RT-R-MDA-MB-231 cells, suggesting that ESM-1 could be a therapeutic target through which MBZ shows an anticancer effect in breast cancer." (PMID 34500557, 2021). "Finally, we confirmed the role of ESM-1 in tumorigenesis in a mouse xenograft model by subcutaneous injecting normal or ESM-1 expressing 4T1 or RT-R-4T1 murine breast cancer cells into athymic nude mice." (PMID 32466580, 2020). "Higher gene expression score of ESM-1 gene was strongly associated with worse overall survival (OS) in the triple-negative breast cancer (TNBC) and hormonal receptor (HR)-positive/HER2-negative subtype in METABRIC cohort, HER2+ subtype in TCGA-BRCA and SCAN-B breast cancer cohorts." (PMID 34072157, 2021). "Based on our hypothesis that ESM-1 is an important prognostic factor for aggressive subtypes of breast cancers, we found that a high expression score of ESM-1 was associated with a higher grade and higher stages of breast cancer patients." (PMID 34072157, 2021). "Moreover, in human breast cancer, ESM1 was correlated with DLL4 in the GEPIA database (R = 0.34, p = 0) and DLL4 was increased in ESM1-treated HUVEC cells." (PMID 36428773, 2022). "However, it is not yet clear what triggers epigenetic changes at the ESM1 promoter in breast cancer cells." (PMID 27888420, 2017). "Interestingly, the expression of ESM1 did not have any impact on the prognosis of other subtypes of breast cancer." (PMID 27888420, 2017). "However, the expression levels of ESM-1 at the metastatic sites, its role in aggressive breast cancers, and whether it could be a prognostic factor of aggressive types of breast cancer were not investigated before." (PMID 34072157, 2021). "The injection of 4T1 breast cancer cells did not affect plasma concentration of the following biomarkers of endothelial dysfunction: SDC-1, ESM-1, sVCAM-1, sICAM-1, sE-sel, t-PA, sP-sel, sTie-2, Ang-2, and sFLT (results not shown)." (PMID 36504711, 2022).
colorectal cancer (19 papers, 2013 to 2025). A primary or metastatic malignant neoplasm that affects the colon or rectum. "ESM1 was the protein with the strongest inverse association with colorectal cancer (OR: 0.59 95% CI 0.43–0.80), closely followed by HGF (OR: 0.60 95% CI 0.42–0.85)." (PMID 33664295, 2021). "In addition, several genes included in both models, such as JUP and ESM1, were reported to be associated with the prognosis of colorectal cancer patients by other researchers, which proved that the results of both models were reliable." (PMID 33628243, 2021). "ESM1 promotes angiogenesis in colorectal cancer by activating the PI3K/Akt/mTOR pathway, a mechanism that accelerates tumor progression." (PMID 40722723, 2025). "A model for the early-stage screening of colorectal cancer was created using seven consensus biomarkers (namely ESM1, DHRS7C, OTOP3, AADACL2, LPHN3, GABRD, and LPAR1), and yielded >98% balanced accuracy on external validation." (PMID 39484215, 2024). "ESM1 was identified as a potential serum marker for the early detection of colorectal cancer, participating in cell survival, invasion, and EMT through Akt-dependent inhibition of NF-κB/IκB pathway." (PMID 36522312, 2022). "Yun and his colleagues have found that knockdown of ESM-1 decreased the expression of NF-κB in colorectal cancer and hepatocellular cancer." (PMID 34109132, 2021). "Increased levels of ESM-1 have been found in the sera of patients with colorectal cancer, hepatocellular carcinoma, and acute leukemia." (PMID 29416643, 2018). "In gastric carcinoma and colorectal cancer, high serum levels of ESM-1 can be served as a marker for diagnosis and poor prognosis." (PMID 28514746, 2017). "In colorectal cancer patients, serum ESM-1 levels were significantly higher than those in healthy controls, and positively correlated with histological differentiation, depth of tumor invasion, TNM stage and lymph node metastasis." (PMID 28514746, 2017). "Since either ESM-1 mRNA in colorectal cancer tissues or ESM-1 protein in serum were elevated in both early stage and advanced stage colorectal cancer, ESM-1 is recommended to be a serum biomaker for the early detection of colorectal cancer." (PMID 28514746, 2017). "CA199 expression is FITC-labeled green, CD31 expression is Alexa Fluor® 647-labeled red, through observation, we can clearly find that compared to ESM1-NC, ESM1-mimic represents colorectal cancer cells CA199 and CD31 representing blood vessels are significantly elevated." (PMID 37100467, 2023). "In addition, ESM-1 expression has been reported to be enhanced by HIF-1α in response to hypoxia in human colorectal cancer and to be mediated by NF-κB in IL-1β-induced inflammatory conditions in human chondrocytes." (PMID 36077661, 2022). "Wang revealed that ESM1 might act as a novel prognostic signature of immune-related genes for patients with colorectal cancer." (PMID 34858850, 2021). "Furthermore, a variety of studies have reported that a high level of ESM-1 secretion is found in several cancers, including lung cancer, kidney cancer, colorectal cancer, acute myeloid leukemia, glioblastomas, and BC." (PMID 32466580, 2020). "Moreover, ESM1 had been suggested to play a role on tumor metastasis, migration and vascular invasion in human hepatocellular carcinoma, gastric and colorectal cancers by regulating the expression of MMPs." (PMID 28108731, 2017). "Mounting evidence indicates serum ESM-1 could be an independent poor prognostic factor for gastric cancer and colorectal cancer." (PMID 28514746, 2017). "ESM1 regulates cell growth and the metastatic process by activation of NF-κB in colorectal cancer." (PMID 28678795, 2017). "Similarly, colorectal cancer cells transfected with ESM1 siRNA resulted in cell cycle arrested at G1 phase by inducing PTEN and inhibition of cyclin D1." (PMID 28108731, 2017).
colorectal cancer (continued). "Furthermore, expression of ESM1 had been reported to be correlated with metastasis, migration and vascular invasion in human gastric and colorectal cancer." (PMID 28108731, 2017). "In addition, it has been reported that ESM-1 is expressed preferentially in the tumor endothelium and is also overexpressed in several types of cancers, including gastric cancer, colorectal cancer, hepatocellular carcinoma, non-small lung cancer, ovarian cancer, and brain cancer." (PMID 36077661, 2022). "Additionally, researchers found that the cell viability of the colorectal cancer cell lines COLO205 and SK-HEP1 was reduced up to 15% and 11% respectively after ESM-1 silencing." (PMID 34109132, 2021). "Moreover, recent studies have pointed out that ectopically high levels of ESM1 are observed in multiple cancer types, such as HCC 16, BRCA 20, ESCC 15, PRCA 18, colorectal cancer (CRC) 36, bladder cancer (BCA) 37, HNSC 38, oral squamous cell carcinoma (OSCC) 39, LUAD 17 and gastric cancer." (PMID 36594088, 2023). "In addition, recent reports have suggested that ESM-1 is a biomarker of TNBC and colorectal cancer." (PMID 32466580, 2020). "In addition, ESM1 was reported to promote cancer progression and invasion by regulating numerous pathways, including DLL4-Notch, NF-κB, PI3K-Akt-mTOR, and Wnt/β-catenin signalings in human adrenocortical carcinoma, colorectal cancer, breast cancer, glioma, and prostate cancer." (PMID 36522312, 2022).
endothelial dysfunction (17 papers, 2020 to 2025). In vascular diseases, endothelial dysfunction is a systemic pathological state of the endothelium (the inner lining of blood vessels) and can be broadly defined as an imbalance between vasodilating and vasoconstricting substances produced by (or acting on) the endothelium. "Elevated ESM-1 levels are associated with endothelial dysfunction and have been linked to the severity of sepsis-AKI." (PMID 39201697, 2024). "Recent reports have shown that ESM1 is associated with endothelial dysfunction, hypertension, kidney transplantation, and renal transplant rejection." (PMID 32781625, 2020). "ESM1 is also implicated in endothelial-dependent pathological conditions and is often elevated in conditions linked to endothelial impairment, serving as both a marker and mediator of endothelial dysfunction." (PMID 40332339, 2025). "Recently, serum ESM1 level was revealed to be associated with the severity of SAS and endothelial dysfunction." (PMID 37968862, 2024). "Endocan is an endothelial-cell-specific proteoglycan (ESM-1) and has emerged as an endothelial dysfunction and inflammatory marker in recent years." (PMID 38474287, 2024). "Endocan, also known as endothelial cell-specific molecule-1, is a potential biomarker for endothelial dysfunction." (PMID 39724169, 2024). "ESM-1 is thought to be a biomarker of endothelial dysfunction, whereas Gal-3 is considered to be a biomarker of atherosclerotic plaque progression and instability." (PMID 36388167, 2022). "ESM-1 is an endothelial dysfunction marker and participates in diverse endothelium-dependent pathological disorders, including cancer, sepsis, kidney diseases and cardiovascular disease." (PMID 34109132, 2021). "As ESM1 expression is particularly high in inflamed endothelium, ESM1 is thought to play a role in the pathogenesis of vascular disorders, inflammation, and endothelial dysfunction." (PMID 32781625, 2020). "Additionally, endothelial cell-specific molecule-1 (ESM-1), also known as endocan, has been recognized as an emerging biomarker for endothelial dysfunction." (PMID 40265185, 2025). "Moreover, suPAR serves as a marker of immune activation and prognosis in sepsis, while ESM-1 reflects endothelial dysfunction." (PMID 39201697, 2024). "ESM1 also plays a role in endothelium‐dependent pathological disorders and may be a surrogate endothelial dysfunction marker." (PMID 37968862, 2024). "Several studies have shown that ESM-1 could be a novel biomarker of various diseases with endothelial dysfunction and inflammation, such as newly diagnosed hypertension." (PMID 36675388, 2023). "ESM-1 might be involved in endothelial-related processes, including cell adhesion, angiogenesis, inflammation, and endothelial dysfunction." (PMID 36675388, 2023). "Previously called endothelial cell-specific molecule-1 (ESM1), endocan may be indicative of endothelial dysfunction." (PMID 37189201, 2023). "ESM-1 has been recently studied as a biomarker candidate for endothelial dysfunction and inflammation because increased ESM-1 levels in tissue or serum reflect endothelial activation and neoangiogenesis, which are marked pathophysiological changes involved in inflammation." (PMID 36077661, 2022). "Therefore, we examined the effect of OXA on endothelial cells and found no detectable impact on genes associated with endothelial dysfunction and vascular injury, including Fabp4, Pcdh17, Esm1, and Cd34." (PMID 37697332, 2023). "Endothelial cell-specific molecule 1 (ESM-1), as a molecule capable of contributing to the progress of pathological atherosclerosis and endothelial dysfunction, has been recognized as a potential indicator of endothelial function." (PMID 36388167, 2022).
endothelial dysfunction (continued). "In contrast, the present study elucidates the IRF5-STAT axis as an upstream transcriptional regulator of ESM1 from the endothelial perspective, expanding the regulatory network and providing a theoretical basis for potential SSH therapeutic strategies targeting endothelial dysfunction." (PMID 40332339, 2025).